IL2 (interleukin 2)
Diseases named in the same sentence as IL2 in open-access papers (continued):
Sharing a sentence is not in itself a finding about the gene and the disease.
tumor (continued). "In this case, despite the seemingly positive effect of the immunotherapy and the in vitro cytotoxic activity against tumor cell lines, the NK cells represented only a reduced fraction of the cells expanded with IL-2 (CD3− CD16+); thus, the relative contribution of the NK cells remained uncertain." (PMID 35203609, 2022). "Here, as a proof of concept, we have used ALTEN to culture clinical specimens of precancerous gastric tissue and a breast cancer tumor and study T cell responses to the immunomodulator IL2, ex vivo and within the tumor microenvironment at the single cell level." (PMID 35611998, 2022). "Interestingly, Kv1.3 overexpression corrected the immunosuppressive K+ accumulation in tumor necrotic areas, increased IL-2 and IFN-γ production, reduced tumor burden and prolonged survival of melanoma bearing mice." (PMID 35892822, 2022). "One way to improve the in vivo persistence of CAR-NK cells in the suppressive tumor microenvironment could be by inducing the expression of stimulatory cytokines, such as IL-2, IL-7, IL-15, and IL-21." (PMID 35203609, 2022). "However, attempts to enhance DMXAA-induced anti-tumor responses by combination with an agonist anti-CD40 antibody or IL-2 reduced efficacy." (PMID 36466911, 2022). "While IL-2 biphasic finding, i.e., it can promote immunity and suppress tumorigenesis in early tumor stages, but in mid- to late-tumor stages, IL-2 signaling promotes 5-hydroxytryptophan (5-HTP) production via the STAT5-TPH1 pathway, leading to CD8+ T-cell depletion." (PMID 36419894, 2022). "Finally, we analysed the effect of the combination of allogeneic adoptive eNK cells, IL-2, and pembrolizumab in the control of tumour growth in HCT-116 and DLD-1 cells." (PMID 35747143, 2022). "In 16 patients, tumor biopsies before and under IL-2 treatment were evaluated for immune markers." (PMID 35158808, 2022). "Moreover, the released AP upregulated IL-2 expression, but downregulated IL-10, indicating that it has potential to restore the Th1/Th2 immune balance in the tumor microenvironment." (PMID 35664731, 2022). "However, these strategies can only bring IL-2 to tumor sites, and strategies to target IL-2 effectively and specifically to intratumoral effector T cells instead of other undesired cells have not been discovered thus far." (PMID 35104810, 2022). "Efficient tumor-targeted co-delivery of PD-L1 siRNA and IL-2 Pdna achieves tumor-specific expression of IL-2 and down-regulation of PD-L1, increases infiltration and activation of CD8+ T cells in HCC, and induces a strong tumor-suppressive effect in HCC in synergy with a vaccine." (PMID 36014696, 2022). "By contrast, an external treatment that increases Interleukin-2 (IL-2) could kill the tumor cells faster, at t = 200 h." (PMID 37420422, 2022). "For IL-2 therapy of a single lesion, tumor exposure alone sufficiently predicts response." (PMID 35013154, 2022). "However, IL-2 administration to cancer patients has increased Treg cells at the tumor site which play a fundamental role in immune system inhibition and anti-tumor responses." (PMID 35354847, 2022). "Novel attempts to improve the anti-tumor potential of IL-2 in the clinics have been recently made." (PMID 36569901, 2022). "Intratumoral delivery of the cytokine interleukin-2, had little effect by itself but when combined with anti-CD40, caused local regression and, importantly regression of a distal untreated tumor, possibly due to the induction of inflammation within the tumor." (PMID 35431929, 2022). "An increase in N-(4-[18F]fluorobenzoyl)-interleukin-2 ([18F]FB-IL-2) uptake in mice models when tumors were either irradiated or immunized was shown, and further increase in tumor tracer accumulation was observed when treatment were combined, indicating a synergistic effect." (PMID 35099641, 2022).
tumor (continued). "IL1β, IL-2, IL-12, TNF-α, and IFN-γ, known as Th1 cytokines, are associated with good prognosis in many malignancies, whereas Th2 cytokines (IL-4, IL-5, and IL-10) are associated with tumor growth and metastasis." (PMID 36090972, 2022). "Additionally, the current study shows the consequences of the TBI/IL-2 combination regarding therapeutic outcomes and immunological profiles in lymphoid and tumor tissues." (PMID 36497152, 2022). "In serum of CT26 tumor-bearing mice, there was extensive overlap with the factors detected in CT26-conditioned media: following mediators identified in conditioned media showed at least a 1.2-fold increase in CT26 tumor-bearing mice: IL-1α, IL-2, IL-13, CCL2/5/19, LIX, CX3CL1, CXCL1/2/10 and CCL19." (PMID 35962398, 2022). "Elevated infiltration of activated immune cells, in turn, resulted in higher levels of Th1-related cytokines and chemokines, and higher infiltration of IFN-γ and IL-2 expressing T cells in the tumour tissues after CAR(NAP) T-cell treatment compared with CAR T-cell treatment." (PMID 35379957, 2022). "Further study of IL-2 immunocytokines of different sizes or dosing frequencies may reveal an optimum circulation time that allows sufficient tumor enrichment while maintaining minimal binding to the systemic sink." (PMID 36712341, 2022). "Importantly, the number of splenocytes secreting IFN-γ, IL-2, and IFN-γ/IL-2 in response to stimulation with peptides A1–15 and A76–90 was inversely correlated with the total tumor volume." (PMID 36612231, 2022). "Organotypic tumor spheroids retain the native tumor stroma as well as many cell types, and lymphocyte populations can be maintained by supplementing IL-2 to sustain their growth within the spheroids or by adding PBMC or tumor-infiltrating lymphocytes derived from the same sample." (PMID 35892819, 2022). "Under IL-2, these cells clearly show a more tumor infiltrative behavior compared to baseline." (PMID 35158808, 2022). "However, due to the high expression of IL-2 receptors on Treg cells, it is difficult to deliver enough IL-2 to CD8+ T cells in the tumor while avoiding systemic toxicity." (PMID 35104810, 2022). "Mice treated with Salmonella or Alb-IL2 alone showed reduced tumor growth." (PMID 35962391, 2022). "Indeed, a significant (p < 0.001) inhibition of tumor growth was observed: tumor size at the end of the 11-day evaluation period reached 502 mm3 in the control group and 186 mm3 in the IL-2 group." (PMID 35954434, 2022). "Interestingly, our data demonstrated a synergistic effect with Salmonella and Alb-IL2 immunotherapy that resulted in robust tumor control that was dependent on T cell immunity." (PMID 35962391, 2022). "Tumor specific activation of CAR T promotes IL-2 that upregulates T reg population." (PMID 35617812, 2022). "IL-15, a type I cytokine together with IL-2, IL-4, IL-7, IL-9, and IL-21, promotes survival of T, B, and NK cells by binding to IL-15α, encoded by IL15RA, negatively regulating both carcinogenesis and tumor growth." (PMID 36432658, 2022). "We hypothesized that the addition of a synthetic cytokine circuit producing IL-2 might enhance tumor control by NY-ESO-1 T cells." (PMID 36520915, 2022). "Notably, RCE plus Oxa caused on average 20.5-and 1.8-fold increases in the levels of released IL-2 and GrB, respectively, suggesting that hPD-1 tumor-infiltrating CD8+ T cells activated by combination therapy secrete IL-2 and GrB." (PMID 36139451, 2022). "Blocking of the IL-2 receptor of Tregs or anti-IL2 therapy could lead to improved sensitivity to tumor antigens in conventional T cells by reducing Treg activity." (PMID 36428581, 2022). "In the 1980s, Rosenberg and his group were the first to confirm that treating metastatic melanoma patients with autologous tumor-infiltrating lymphocytes (TILs) and IL-2 could achieve objective regression." (PMID 36428748, 2022). "The tumor fragments or single-cell suspensions are then cultured in a complete medium with IL-2." (PMID 36077696, 2022).
tumor (continued). "These APCs inhibit T-cell activation by expressing PD-L1 and by establishing interactions with PD-1 on T cells, and concurrently, they can secrete a substantial number of cytokines such as IFN-γ, IL-2 and IL-10, which indirectly promote PD-L1 expression in tumor cells and APCs41–43." (PMID 35165282, 2022). "However, IL-2 can also activate Treg cells, which inhibits the anti-tumor immune response of T cells." (PMID 36569954, 2022). "The effect of NK cells on the GVL effect after IL-2 therapy should be tested by the experiments with the other settings, which may contribute to identifying the responsible cells for the anti-tumor activity increased by IL-2 therapy." (PMID 35983059, 2022). "Using IL-2 as an example, here we report the role of its pharmacokinetics in controlling therapeutic efficacy after intratumoral injection and define strategies to maximize anti-tumor effect by tuning local retention." (PMID 35013154, 2022). "Similarly, IL-15 in combination with IL-2 boosted the proliferation as well as the in vitro anti-tumor activity of ZOL-expanded Vδ2 T cells." (PMID 36429001, 2022). "Among other examples are the immunocytokine format for directing IL-2 to the tumor cells, IL-2 fusion with the IgG-Fc region to increase the molecule half-life, or increasing the half-life and changing molecular properties with site-directed pegylation that has been assayed." (PMID 36059465, 2022). "Besides, the functional CD8+ T cells, which produce various cytokines (TNFα, IFNγ, GZMB, and IL2), were increased in the tumor from VEGF-C mRNA group." (PMID 35301438, 2022). "It is arguable that intratumoral treatment with IL-2 may have diverse effects on the tumor microenvironment, i.e., not only induction of CD8+ cytotoxic T cells or NK cells but also induction of regulatory T cells (Tregs)." (PMID 35158808, 2022). "Furthermore, the iNK cells can produce IFN-γ and TNF-α in the presence of PMA/ionomycin, K562 tumor cells, or IL-2." (PMID 36344493, 2022). "In addition, the interaction of IL-2 with its alpha receptor and expansion of regulatory T cells will activate immunosuppressive responses and reduce T cell-mediated anti-tumor activities." (PMID 35354847, 2022). "Interestingly, preclinical data showed, that the CD28zeta format has also a positive effect on regulatory T cells in the tumor microenvironment because of its high capacity to induce IL-2 secretion." (PMID 36032080, 2022). "Given this, it is possible that accumulation of Alb-IL2 in the tumor and lymph node could be playing a role in the observed antitumor responses." (PMID 35962391, 2022). "Indeed, tumor-derived exosomes induce IL-2 reactivity to regulatory T cells and inhibit its access to cytotoxic cells, thus facilitating the escape of cancer cells." (PMID 36741380, 2022). "Most studies focus on using antitumor antigens to bring IL-2 into tumor tissues." (PMID 35104810, 2022). "Although in this work we only observed minor nanobody-driven benefits for small IL-2 immunocytokines delivered intravenously, there may be other situations where tumor-targeting could lead to larger improvements for systemically delivered cytokines." (PMID 36712341, 2022). "The more efficient the vector, the more viruses infect tumor cells and the more circulating cytokines might be expressed, which might lead to increased toxicity of circulating IL2." (PMID 35799600, 2022). "Moreover, IL-2 is known to control and boost the growth of regulatory T-cells within the tumor microenvironment thus impeding its own anti-tumor activity." (PMID 35474089, 2022). "This signaling pathway dampens T cell receptor (TCR) signaling and CD28 signaling for T cell activation and the secretion of inflammatory cytokines, such as interferon-γ (IFN-γ), tumor necrosis factor (TNF), and interleukin-2 (IL-2), suppressing the cytotoxic effect on tumor cells." (PMID 36389700, 2022).
tumor (continued). "Furthermore, the IHS influenced T cells in ApcMin/+ mice by increasing the interleukin (IL)-2 and decreasing the IL-5, -6, and -10 levels, thus suppressing tumor development." (PMID 36014805, 2022). "Previous studies showed that PD-1 blockade led to the augmentation of effector T cells in tumor sites, increasing the cytolytic activity of tumor-specific cells, increasing production of IL-2, INF-γ, TNF-α, IL-17, and IL-6, and decreasing the production of the Th2 cytokines such as IL-5 and IL-13." (PMID 35996120, 2022). "Intra-tumor increased IL-2, IFN-γ, and GM-CSF and decreased IL-6 staining." (PMID 36358823, 2022). "Intravenously delivered IL-2 with picomolar affinity to EIIIB had only a modest impact on tumor growth compared to untargeted IL-2 in two different tumor models.We have previously showed that the biodistribution of large format IL-2 immunocytokines is dominated by the IL-2 moiety." (PMID 36712341, 2022). "Moreover, it is found that IL-2 and others can effectively enhance T cell-mediated tumor immunotherapy effect by inhibiting Tregs function, targeting exhausting Tregs, or interfering with their recruitment to TME." (PMID 36202899, 2022). "The increase in cytotoxic activity is associated with enhanced tumor cell killing, although IL-21 neither synergizes nor interferes with IL-2." (PMID 36429001, 2022). "The combination therapy with IL-2 and IFN-α and chemo-radiotherapy may potentiate the anti-tumor capacity of IL-2 in RCC patients, as shown by improved ORR." (PMID 36510217, 2022). "In order to test whether this photodynamic chemotherapy could mediate the immune response in tumor site, we measured the mRNA expression level of Il-2, Il-6, Il-10, Tnf-α, Tgf-β and Inf-γ in tumor issues." (PMID 35999549, 2022). "Increased IL2 amounts at local tumor sites favor the antitumor response, though increased circulating IL2 induced by the recombinant virus may be toxic." (PMID 35799600, 2022). "The results revealed that local administration of recombinant IL-2 proteins could control the tumor growth, which was more prominent with mutant IL-2 than the wIL-2." (PMID 35354847, 2022). "This was done in the hopes of augmenting an IL-2-mediated anti-tumor immune response." (PMID 34122442, 2021). "Interestingly, apoptosis of the tumor cells, infiltration of CD8+ cells, as well as amplified IFN-γ and IL-2 levels were only realized in PSMA+ PC3 tumor cells." (PMID 34868907, 2021). "With this under consideration, Poschke and colleagues hypothesized that combining TILs infusion and tumor lysate DC vaccination could circumvent the need for preconditioning and IL-2." (PMID 34830973, 2021). "We hypothesized that immunotherapy with anti-CTLA-4 and bempegaldesleukin (BEMPEG; NKTR-214), a CD122-preferential IL2 pathway agonist, after primary tumor RT or resection would reduce metastases in a syngeneic murine NSCLC model." (PMID 33937052, 2021). "Therefore, IL-7 and IL-15 can be potential alternatives to using IL-2 in the generation of tumor specific T cells." (PMID 34012451, 2021). "CD4+T cells can secrete IFN-γ, IL-2, and TNFα cytokines to interfere with tumor development." (PMID 34804019, 2021). "Over the past three decades, efforts have focused on circumventing IL-2-related toxicities by engineering methods to localize IL-2 to the tumor or secondary lymphoid tissue, preferentially activate CD8+ T cells and NK cells, and alter pharmacokinetic properties to increase bioavailability." (PMID 34790830, 2021). "Radiolabelling of human recombinant IL-2 with short-lived positron-emitting radionuclides such as fluorine-18 (18F−) have already been shown to provide a tool for non-invasive imaging of activated tumour infiltrating lymphocytes (TILs) in cancer." (PMID 33808813, 2021). "First of all, IL-2 treatment in the era of immune checkpoint inhibitors seems anachronistic, but at the time of study design and approval, none of the modern immunotherapies were available for these types of tumour." (PMID 33800511, 2021).
tumor (continued). "In addition, some CD8+ T cells express tumor-reactive T-cell receptor (TCR) when analyzed in vitro after exposure to IL-2 and mediate anti-tumor reactivity." (PMID 33602230, 2021). "Our data suggests that IL-2 activated and expanded NK cells could be well suited to function in a tumor environment where glucose availability is limited." (PMID 34094908, 2021). "The resected melanoma is split up into multiple tumor fragments individually grown in IL-2." (PMID 33804800, 2021). "In both tumor types pFUS increased IL1α, IL1ß, IL2, IL6, IL12p40, IL15, IL17, TNFα, and VCAM." (PMID 33801627, 2021). "In order to analyze in more detail the immunosuppressive activity of PMN-MDSC, these cells were isolated from PB of tumor patients and co-cultured with fresh, short-term and long-term IL2-activated allogenic NK cells at 1:1 ratio, referred in the text as “conditioned” NK cells (cond)." (PMID 35116033, 2021). "Besides, IL-2 level in HT treated tumor displayed a slight increase, while the concentrations of TNF-α and IL-10 showed no obvious changes as compared to control group." (PMID 33986437, 2021). "LAK cells were generated from freshly isolated peripheral blood mononuclear cells (PBMCs) that were cultured in the presence of interleukin-2 (IL-2) and were further characterized by their ability to kill NK-resistant human tumor cells, even though most LAK cells express NK markers." (PMID 33807011, 2021). "sh‐c‐Myb or PD‐L1 alone into FLO‐1 cells increased Fas, IFN‐γ, and IL‐2 expression, but decreased FasL, IL‐4, and IL‐10 expression in the tumor tissues, and cotransfection of sh‐c‐Myb and PD‐L1 showed more significant trends compared with transfection of sh‐c‐Myb or PD‐L1 alone." (PMID 34586738, 2021). "They concluded that the tumor growth could be reduced if we use treatments like IL-2 therapy, adoptive T cell therapy which boosts the immune system, and antibody therapy which blocks tumor-induced immuno-suppression." (PMID 34721555, 2021). "In addition, prolonged IL2 exposure can stimulate regulatory T-cells (Tregs), inhibiting the tumor-targeting immune response." (PMID 33579033, 2021). "Tumor size inversely correlated with IN-specific IFN-γ/IL-2 T-cell response." (PMID 34199989, 2021). "Whilst IL-2 and IL-15 overlap in several key functions, including supporting the proliferation and activation of NK cells, IL-2 can support the persistence of regulatory T cells (Tregs), which is an undesirable feature in the context of anti-tumour immunity." (PMID 35008227, 2021). "Constitutive expression of IL-2 by 1st generation CD19-CAR T cells improved the tumor-free survival of mice with disseminated lymphoma compared to CAR T cells alone, although other γc cytokines were associated with greater improvements in survival and longer persistence of CAR T cells." (PMID 34177932, 2021). "However, recent advances in our understanding of the mechanisms of cytokine anti-tumor effects has potentially opened new avenues for the clinical use of IL2." (PMID 33579033, 2021). "In syngeneic tumor-bearing mice, intravenous administration of the IL-2 variant RNA-LNP expanded spontaneous anti-tumor T-cell responses without significant elevation of Tregs, leading to a strong increase of the CD8+ T cell to Treg ratio." (PMID 33858437, 2021). "One study that combined anti-FAP CAR T cells along with total body irradiation and IL-2 injections showed limited anti-tumor efficacy as well as enhanced side effects including bone marrow toxicity and cachexia in numerous tumor types such as those of the head and neck, lung, and pancreas." (PMID 34200702, 2021). "We demonstrated that mEHT facilitated the migration and tumor infiltration of both the primary, ex vivo expanded NK cells and the genetically modified, IL-2 producing NK92-MI cells administered subcutaneously one day after loco-regional mEHT treatment of tumor bearing mice." (PMID 33732640, 2021).